METTL14 (methyltransferase 14, N6-adenosine-methyltransferase non-catalytic subunit)
Diseases named in the same sentence as METTL14 in open-access papers (continued):
Sharing a sentence is not in itself a finding about the gene and the disease.
tumor (continued). "As a core component of the m6A methyltransferase complex, METTL14 is known to suppress tumorigenesis; however, its specific role in tumor angiogenesis remains elusive." (PMID 42213490, 2026). "Previous studies examining the functions of METTL3 and METTL14 in BCa have reported both tumour suppressor and oncogenic roles and have implicated METTL3 and METTL14 in several mechanisms." (PMID 41310336, 2025). "Membrane fluidity regulation is critical for tumor invasion and metastasis, and our analysis revealed that silencing METTL14 decreased membrane fluidity, while METTL14 overexpression increased membrane fluidity in CM cells." (PMID 41316357, 2025). "Another study focused on the role of METTL14 in TAMs, revealing that its loss promotes CD8 + T cell dysfunction and tumor growth." (PMID 40176140, 2025). "For instance, high expression of the RNA N6-adenosine methyltransferase METTL14 in tumor cells increases the proportion of PD-1 + TAMs, which lack the ability to engulf tumor cells, thus inhibiting macrophage recognition and phagocytosis of tumor cells." (PMID 40176140, 2025). "METTL14 inhibits tumor proliferation by promoting the degradation of SOX4 mRNA and has an anticancer effect." (PMID 41446042, 2025). "The combination of METTL14 inhibitors with PD-1/PD-L1 antibodies synergistically remodels the tumor immune microenvironment, enhancing antitumor immunity and effectively suppressing cancer progression." (PMID 41164187, 2025). "In summary, these findings identify ZFP14 as not only a tumour‐suppressor in ccRCC but also an important participant for METTL14 to inhibit ccRCC progression." (PMID 39936533, 2025). "By targeting the PI3K/AKT/mTOR and EMT pathways as tumor suppressors, METTL14 can inhibit the progression and invasiveness of GC cells." (PMID 41312360, 2025). "METTL3 and METTL14 participate in most m6 A modifications of mRNA and act as tumor suppressors or oncoproteins in various cancers." (PMID 40483535, 2025). "Here, we show that METTL14 is essential for Treg differentiation and suppressive function, connecting its epitranscriptomic activity to the modulation of immune tolerance and tumor immune escape." (PMID 41164187, 2025). "Together, these observations underscore METTL14 as a central hub linking epitranscriptomic regulation to tumor immune modulation, which is the core argument of this review." (PMID 41164187, 2025). "Despite extensive evidence highlighting the pivotal role of METTL14 in regulating tumor progression and immune cell function, several limitations must be acknowledged to provide a balanced perspective." (PMID 41164187, 2025). "Most regulators, such as METTL3, YTHDF1, IGF2BP3, and RBMX, were upregulated in tumor tissues, while METTL14 and ZC3H13 were downregulated." (PMID 40916616, 2025). "Two studies also indicate that METTL14 acts as a tumor suppressor by facilitating DNA repair or modulating glycolysis." (PMID 38853928, 2025). "Macrophages are highly plastic immune cells that critically influence tumor progression, and METTL14 has emerged as a regulator of TAM recruitment and function." (PMID 41164187, 2025). "It has been reported that METTL14 abundance is elevated in pancreatic cancer samples and promotes tumor cell growth/proliferation, migration, invasion and colony formation by the m6A-dependent mechanisms." (PMID 40734692, 2025). "In agreement with our findings that increased METTL14 expression correlated with more favourable clinical prognostic factors and outcomes, TCGA GDC transcriptomic data showed decreased METTL14 expression in tumour tissue compared with normal breast tissue." (PMID 41310336, 2025). "Aberrant METTL14 expression correlates with tumor progression and immune evasion, underscoring its potential as a predictive biomarker and therapeutic target." (PMID 41164187, 2025).
tumor (continued). "In most tumors, METTL14 functions as a tumor suppressor by reducing m6A levels within cancer cells through its activity as an m6A methyltransferase, thereby inhibiting tumor development and progression." (PMID 40567896, 2025). "Functional and in vivo studies confirm the glycolysis–lactate–PD-1 axis as a critical mechanism by which METTL14 drives TAM-mediated tumor progression, identifying it as a potential therapeutic target." (PMID 41164187, 2025). "METTL14 can inhibit the self-renewal of tumor-initiating cells and bladder tumorigenesis through m6A modification of Notch1." (PMID 40986143, 2025). "Together, these findings illustrate METTL14 m6A-independent versatility, reinforcing its significance in cell senescence, differentiation, and pathological processes relevant to tumor immunity." (PMID 41164187, 2025). "Against this backdrop, METTL14 and its mediated m6A modification have emerged as critical factors linking epigenetic regulation with tumor immunity." (PMID 41164187, 2025). "METTL14 exerts anticancer effects, while others promote translation and autophagy, enhancing tumor stemness." (PMID 41446042, 2025). "Collectively, these data supported that SLC27A5 deficiency facilitates the expression of PABPC1 and short 3'UTR isoforms of METTL14, thereby inhibiting METTL14 expression and promoting tumor progression." (PMID 40290127, 2025). "This section will focus on how METTL14 modulates PD-1/PD-L1 and related molecules to regulate T cell function and tumor immune evasion, emphasizing its critical role in immunotherapy efficacy." (PMID 41164187, 2025). "METTL14 has also been shown to be downregulated and exhibit tumour suppressive effects in some cancers." (PMID 40356909, 2025). "Understanding these regulatory pathways will provide crucial insights into the central role of METTL14 in tumor immune modulation and lay the foundation for developing METTL14-targeted therapeutic strategies." (PMID 41164187, 2025). "Taken together, these findings underscore METTL14 as a master regulator of immune checkpoint signaling and tumor immune escape, providing a mechanistic rationale for targeting METTL14 to enhance immunotherapy responses." (PMID 41164187, 2025). "In various cancer tissues, the METTL3 and METTL14 complexes play diverse roles, functioning as both oncogenes and tumor suppressors." (PMID 39802639, 2025). "A subcutaneous injection test indicated that the METTL14 overexpression significantly inhibited tumour growth." (PMID 39827141, 2025). "In summary, METTL14 versatile functions and finely tuned regulatory mechanisms provide a mechanistic basis for its central role in immune regulation and tumor biology, setting the stage for a detailed examination of its specific molecular functions." (PMID 41164187, 2025). "In a 2021 study, it was shown that METTL14, under‐expressed in ccRCC, impedes tumour spread by modulating BPTF expression through the m6A‐dependent mechanism." (PMID 39936533, 2025). "In this study, ZFP14 was identified for the first time not only as a tumour suppressor in ccRCC but also as a crucial target of METTL14‐mediated m6A, with IGF2BP2 participating." (PMID 39936533, 2025). "In summary, the mechanistic and therapeutic significance of METTL14 positions it as a pivotal link between epitranscriptomic regulation and tumor immune responses, setting the stage for a deeper discussion of its role in immunotherapy efficacy." (PMID 41164187, 2025). "The opposite effect of another core protein of methyltransferase complex METTL14 was observed in the context of metastatic ability and tumor recurrence in HCC models in vivo and in vitro." (PMID 41157107, 2025). "These multilayered regulatory mechanisms not only maintain METTL14 homeostasis under normal conditions but also enable its dynamic responses to inflammation, immune signaling, and tumor microenvironmental changes." (PMID 41164187, 2025).
tumor (continued). "The key m6A-related genes METTL3 and METTL14 were reported to be active components of the m6A methyltransferase complex and correlated with tumor proliferation, differentiation, tumorigenesis, invasion, and metastasis." (PMID 40123906, 2025). "METTL3 emerges as a clinically validated prognostic and immunoregulatory biomarker in breast cancer, whereas METTL14 is correlated with both survival outcomes and tumor-infiltrating lymphocyte dynamics in rectal adenocarcinoma." (PMID 40986143, 2025). "METTL14 can inhibit tumor proliferation and invasion by modulating the PI3K/AKT/mTOR signaling pathway." (PMID 41312360, 2025). "This study offers fresh perspectives on the possible function of METTL14 in tumor immune evasion through the suppression of cell surface HLA class I expression, although further characterization is needed." (PMID 41316520, 2025). "While regulators like METTL3 and FTO largely drive oncogenesis, others, most notably METTL14, exert potent tumor-suppressive effects, underscoring the critical importance of context-specific understanding." (PMID 41312360, 2025). "With growing evidence of the immunoregulatory role of m6A modification, the multifaceted functions of METTL14 within the tumor immune microenvironment (TME) are being progressively unraveled, underscoring its translational value." (PMID 41164187, 2025). "METTL3 promotes tumor proliferation and PD-L1-mediated immune escape while METTL14 can inhibit tumorigenesis in the bladder." (PMID 40133252, 2025). "This binding disrupts WTAP-methyltransferase-like protein 3 (METTL3)–methyltransferase-like protein 14 (METTL14) complex formation, reducing overall m6A modification in tumor cells, inhibiting HCC cell growth." (PMID 41181701, 2025). "We sought to explore the biological functions of ZFP14 in ccRCC, particularly its role in METTL14's tumour‐suppressing effects, as previously demonstrated." (PMID 39936533, 2025). "Given the aberrant m6A levels and METTL3 and METTL14 expression levels, we proceeded to investigate their potential roles in the tumour biological behaviour of GBC." (PMID 40785027, 2025). "In cervical cancer, METTL14 is overexpressed and enhances tumor glycolysis, producing lactate that upregulates PD-1 expression in TAMs." (PMID 41164187, 2025). "First, the functions of METTL14 are highly context-dependent, varying across tumor types, immune cell subsets, and microenvironmental conditions." (PMID 41164187, 2025). "Previously recognised as a tumour suppressor, METTL14's mechanisms remain inadequately understood despite prior studies." (PMID 39936533, 2025). "METTL14 expression in CC tissues was significantly correlated with tumor size, differentiation, lymph node metastasis, and FIGO stages." (PMID 38738555, 2024). "Studies on methyltransferases in kidney cancer, such as ccRCC, demonstrate that both METTL3 and METTL14 play as tumor suppressors." (PMID 39136000, 2024). "Knockdown of METTL3 has been observed to alter the malignant phenotype across various tumor types, whereas multiple studies have indicated that elevated expression of METTL14 inhibits tumor proliferation and migration via m6A-dependent mechanisms." (PMID 38965238, 2024). "One study identified that the deficiency of N6-methyladenosine methyltransferase Mettl14 in TAMs can inhibit CD8+ T-cell infiltration and promote tumour growth." (PMID 39073672, 2024). "In vitro, knockdown of METTL14 significantly inhibited autophagy and promoted malignant progression, and in vivo promoted tumor growth and metastasis." (PMID 39289775, 2024). "In the subcutaneous tumour model, METTL14 knockdown resulted in a delayed growth of xenograft tumours." (PMID 39021049, 2024). "The regulatory role of RNA N6-methyladenosine (m6A) in gene expression has attracted significant attention, and the impact of methyltransferase-like 14 (METTL14) on tumor progression has been extensively studied in various types of cancer." (PMID 38649363, 2024).
tumor (continued). "IHC performed on paraffin sections of 80 NPC and 42 adjacent non‐tumour NPE tissues demonstrated elevated METTL14 protein expression in NPC tissues." (PMID 39021049, 2024). "We identified the involvement of the “METTL14-YWHAH-PI3K/AKT” axis, in which METTL14 promotes tumor growth and invasion in NB cells by activating the PI3K/AKT signaling pathway." (PMID 38649363, 2024). "A pan-cancer analysis leveraging data from TCGA revealed that, in contrast to normal tissues, mRNA expression levels of METTL3 are significantly upregulated in tumor tissues, whereas the expression levels of METTL14 remain unchanged." (PMID 38965238, 2024). "Western blot analysis revealed that knockdown of METTL14 decreased METTL14 protein levels in tumor tissues." (PMID 38725005, 2024). "Of note, as a central component of the m6A methylated transferase complex, METTL14 has been found to be dysregulated and partake in different tumor development." (PMID 38956710, 2024). "Upregulated RASAL2-AS1 promoted tumor weight and tumor volume, which was counteracted by silencing METTL14." (PMID 38528591, 2024). "METTL14 plays dual roles as both an oncogene and a tumor suppressor gene in regulating the onset and progression of various cancers." (PMID 39138186, 2024). "In vivo assays revealed that METTL14 knockdown inhibited tumor growth and enhanced the response to PD-1 immunotherapy." (PMID 38725005, 2024). "After 30 days, the depletion of METTL14 significantly restricted tumor volume and weight compared to the shNC group." (PMID 39138186, 2024). "Knockdown of METTL14 effectively suppressed tumor cell proliferation, migration, and invasion both in vitro and in vivo." (PMID 39138186, 2024). "We observed a significant increase in METTL14 expression in tumor tissues from LUAD patients compared to adjacent normal tissues, along with high levels of m6A modification." (PMID 39138186, 2024). "Beyond that, western blot analysis exhibited that the protein levels of METTL14, AOC1, Cyclin D1, Bcl-2, and N-cadherin were clearly lower in tumor tissues derived from sh-METTL14-transfected C666-1 cells." (PMID 38956710, 2024). "Numerous studies have consistently demonstrated the involvement of m6A writers, particularly METTL3 and METTL14, in promoting the survival, proliferation, and invasion of tumor cells." (PMID 38649363, 2024). "First, we analysed the mRNA level of METTL14 in UALCAN database, and found that METTL14 mRNA was highly expressed in BC tumour tissues." (PMID 38263865, 2024). "Among m6A writers, METTL3 and METTL14 are primarily investigated for their roles in tumor angiogenesis." (PMID 39098905, 2024). "The in vivo LDA also demonstrated that the overexpression of wild-type METTL14 decreased, while the inactive METTL14 mutant increased, the tumor incidence." (PMID 39563370, 2024). "Developing METTL14‐based inhibitors targeting ANKRD22 to impede lipid metabolism in tumour cells emerges as a promising strategy for future NPC treatment." (PMID 39021049, 2024). "Nevertheless, in certain cancers, METTL3 and METTL14 demonstrate divergent effects on tumor progression." (PMID 38965238, 2024). "In summary, the m6A writers METTL3 and METTL14 play important roles in the occurrence and development of tumors by regulating specific targets or pathways that affect tumor angiogenesis." (PMID 39295872, 2024). "Knockdown of METTL14 reduces the circORC5 m6A levels, increasing circORC5 expression and inhibiting tumor progression through the miR-30c-2-3p/AKT1 substrate 1 (AKT1S1) axis." (PMID 38856795, 2024). "IHC analysis further confirmed that METTL14 knockdown led to a lower number of Ki67 positive cells in tumor tissue sections." (PMID 39138186, 2024). "Through a combination of RNA sequencing and MeRIP-sequencing, we identified numerous altered genes and confirmed that IGF2BP2 enhances G6PD mRNA stability after METTL14-mediated m6A modification, thereby promoting tumor growth and metastasis." (PMID 39138186, 2024).
tumor (continued). "METTL14 also regulates the glycolytic pathway and inhibits tumor proliferation through the USP48-SIRT6 pathway." (PMID 38965238, 2024). "METTL14 also acts as a tumor suppressor in bladder cancer and renal cell carcinoma by inhibiting Notch1 and P2RX6 separately through m6A modification." (PMID 39457524, 2024). "In vivo studies using nude mice with subcutaneously transplanted LUAD cells demonstrated that stable METTL14 knockdown led to notably reduced tumor volume and weight, along with fewer Ki67-positive cells and lung metastatic sites." (PMID 39138186, 2024). "In summary, our in vitro and in vivo experiments have elucidated the differing roles of METTL3 and METTL14 proteins in tumor cell proliferation capability." (PMID 38965238, 2024). "Another methyltransferase, METTL14, inhibits tumour progression in clear cell renal cell carcinoma (ccRCC) by mediating m6A modification of Phosphatase and tensin homolog (PTEN) mRNA." (PMID 38572667, 2024). "METTL14 is also decreased in colorectal cancer and represses tumor progression by promoting SOX4 expression and reducing XIST in an m6A-YTHDF2-dependent manner, and by promoting pri-miR-375 processing through an m6A/DGCR8-dependent mechanism." (PMID 39457524, 2024). "For METTL14, macrophage‐specific elimination of METTL14 was found to impair tumour clearance by CD8+ T cells due to dysfunction‐driven CD8+ T‐cell differentiation." (PMID 38572667, 2024). "Of note, they also found a tumor promoting effect of METTL14 in the proliferation and migration of liver cancer cells." (PMID 38545555, 2024). "This suggests that the promoting effect on tumor growth is a result of the interaction of RASAL2-AS1 with METTL14 in the xenograft model." (PMID 38528591, 2024). "The biological role of METTL14 on NPC tumor growth was examined by the xenograft tumor model in vivo." (PMID 38956710, 2024). "The changes in these down-stream target genes further support the claim that METTL3 and METTL14 have tumor suppressor functions in GSCs." (PMID 38398118, 2024). "Research has shown that METTL14/ALKBH5 affects tumor growth and progression by regulating key cell cycle- and angiogenesis-related transcripts." (PMID 39295872, 2024). "Immunohistochemical analysis of tumor sections revealed a significant reduction in METTL14 expression and a corresponding marked decrease in Ki67 expression in METTL14-knockdown tumor tissues compared to those in the control group." (PMID 38649363, 2024). "METTL14 (Methyltransferase-like 14) is the central component of the m6A methyltransferase complex and acts as both an oncogene and tumor suppressor gene." (PMID 39457524, 2024). "As a homolog of METTL3, METTL14 shares some similarities, but METTL14 is downregulated in HCC, is closely associated with tumor metastasis, and plays a regulatory role in the process of HCC tumor metastasis." (PMID 39229278, 2024). "Nevertheless, recent investigations reveal inconsistent expression levels and prognostic significance of METTL3 and METTL14 across various tumor types, challenging their consistent functional engagement in neoplastic contexts." (PMID 38965238, 2024). "METTL14 is highly expressed in distinct tumor types and boosts stemness by enhancing SOX2 mRNA stability upon m6A modification." (PMID 37142269, 2023). "Increased m6A mediated by METTL3/METTL14 promotes tumorigenesis and tumor metastasis by regulating the stability and translation of oncogenic mRNA in several epithelial cancers." (PMID 37891533, 2023). "Based on available limited data, though METTL3 has a preference to exert an oncogenic effect, it is worthwhile mentioning that METTL14 exhibits dual effects but tends to present a protective, tumour‐suppressing role in cancers." (PMID 36162823, 2023).